FSTL3 (follistatin like 3)
Diseases named in the same sentence as FSTL3 in open-access papers (continued):
Sharing a sentence is not in itself a finding about the gene and the disease.
lung carcinoma (7 papers, 2021 to 2025). "A very recent study came to the same conclusion, that FSTL3 is strongly linked with increased metastatic formation in a mice model of lung cancer." (PMID 34395416, 2021). "Analysis of The Cancer Genome Atlas (TCGA) datasets revealed that FSTL3 was associated with poor survival outcomes in multiple cancers, including ovarian, colorectal, pancreatic and lung cancers; in comparison, FST had a weaker correlation of poor prognosis for ovarian cancer." (PMID 41029436, 2025). "Since FSTL3 is an oncogene in lung cancer, DSCAM-AS1-mediated up-regulation of this oncogene can promote carcinogenesis process in this type of tissue." (PMID 34708048, 2021). "Knockdown of FSTL3 remarkably inhibited the aggression phenotype of lung cancer cells." (PMID 36925652, 2023). "Previous studies revealed that the upregulation of FSTL3, mediated by lncRNA DSCAM‐AS1, enhances the proliferation and metastasis of lung cancer cells." (PMID 41395115, 2025). "FSTL3, as an oncogene of the FSTL family, is involved in the occurrence and progression of lung cancer." (PMID 37291533, 2023). "Two additional studies in lung cancer and HCC have shown that knock-down of DSCAM-AS1 downstream target FSTL3 similarly decreases tumor volume." (PMID 34708048, 2021).
lymph node metastasis (6 papers, 2021 to 2025). "High expression of FSTL3 is associated with lymph node metastasis and can serve as a biomarker for extracellular matrix remodeling in colon cancer." (PMID 40595026, 2025). "FSTL3 is also associated with lymph node metastasis, and applied as a biomarker for CRC extracellular matrix remodeling." (PMID 37017587, 2023). "Patients with LUAD and exhibiting elevated levels of FSTL3 expression demonstrated a higher propensity for lymph node metastasis and presented with inferior clinicopathological staging compared to LUAD patients with lower FSTL3 expression." (PMID 38240936, 2024). "FSTL3 in tumors was correlated with lymph node metastasis, clinical stage, tumor size, and intravascular emboli." (PMID 37497410, 2023). "A recent bioinformatics study had identified FSTL3 as a key prognostic gene related to both immune status and lymph node metastasis in CRC36." (PMID 37497410, 2023). "FSTL3 expression is correlated with lymph node metastasis, tumor stage, tumor size, and intravascular emboli and is associated with a poorer prognosis." (PMID 36325361, 2022). "The expression of FSTL3 significantly correlated to lymph node metastasis, staging, tumor size and intravascular emboli (IVE)." (PMID 34395416, 2021).
gastric cancer (5 papers, 2021 to 2023). A primary or metastatic malignant neoplasm involving the stomach. "Univariate Cox analysis of gastric cancer patient clinical features linked to increased FSTL3 expression." (PMID 34425560, 2021). "FSTL3 knockdown caused 50% decrease in gastric cancer cell line MGC-803 colony formation compared to control." (PMID 34425560, 2021). "We also made a synthetic miR-486-5p inhibitor, and delivery of this into gastric cancer cells caused a 1.5-2-fold rise in FSTL3 protein levels; this correlated with a 2.5-fold rise in FSTL3 mRNA levels." (PMID 34425560, 2021). "First, cancer bioinformatics shows a clear association with increased FSTL3 expression in gastric cancer patients." (PMID 34425560, 2021). "Elevated levels of FSTL3 is associated with poor patient prognosis in gastric cancer." (PMID 34425560, 2021). "Finally, FSTL3 mRNA is regulation by miR-486-5p modulates FSTL3 expression and gastric cancer cell-associated responses." (PMID 34425560, 2021). "Whether FSTL3 is a new diagnostic biomarker of gastric cancer requires the collection of more unbiased clinical datasets across the global population." (PMID 34425560, 2021). "FSTL3 is a prognostic biomarker for gastric cancer (GC) and participates in the progression of GC by promoting epithelial‐mesenchymal transition." (PMID 37017587, 2023). "The dysregulation of miRNAs has been implicated in cancer biology; lower miR-486-5p levels and higher FSTL3 expression have been found in gastric cells of patients with gastric cancer compared to that in healthy controls." (PMID 36325361, 2022). "Transfection of this miR-486-5p mimic was transfected into gastric cancer cell line MGC-803: FSTL3 expression was decreased 50%." (PMID 34425560, 2021). "FSTL3 shows promise as a new biomarker for gastric cancer diagnosis and is a new therapeutic target in this disease." (PMID 34425560, 2021). "We then addressed the role of FSTL3 in gastric cancer using in vitro cellular models alongside in vivo animal models." (PMID 34425560, 2021). "Measurement of cell viability showed increased FSTL3 levels promoted gastric cancer cell line SGC-7901 viability; in contrast, FSTL3 knockdown caused decreased cell viability in MGC-803." (PMID 34425560, 2021). "Next, we evaluated the clinical implications of FSTL3 expression in gastric cancer patient prognosis using Kaplan-Meier analysis." (PMID 34425560, 2021). "To further test inference from our bioinformatics studies, we knocked down and overexpressed the expression of FSTL3 in gastric cancer cells." (PMID 34425560, 2021). "We screened for differentially expressed genes from the FSTL3 high and low expression groups in gastric cancer." (PMID 34425560, 2021). "We then assessed the contribution of FSTL3 to gastric cancer cell tumorigenicity using an in vivo animal model." (PMID 34425560, 2021). "FSTL3 expression was lowest in control GES1 cell line; however, FSTL3 levels were raised in all gastric cancer cell lines with the highest expression in MGC-803 and lowest in SGC-7901 cell lines." (PMID 34425560, 2021). "Our studies now provide new insights into how abnormal control of FSTL3 expression regulates gastric cancer development and progression." (PMID 34425560, 2021). "FSTL3 overexpression promoted a 2-fold increase in cell migration compared to control in gastric cancer cell line SGC-7901." (PMID 34425560, 2021). "Normal gastric epithelial cell line GES1 was compared to 5 different gastric cancer cell lines and Western blotting of cell lysates showed clear differences in FSTL3 protein levels." (PMID 34425560, 2021). "Gastric cancer patients thus exhibit increased FSTL3 expression which influences disease progression and survival." (PMID 34425560, 2021). "In a comparison of normal gastric epithelial cells and gastric cancer cell lines, FSTL3 expression was consistently elevated in gastric cancer cells." (PMID 34425560, 2021).
gastric cancer (continued). "These 2 lines were then selected as low and high FSTL3 expressors for testing FSTL3 regulation of gastric cancer cell function." (PMID 34425560, 2021). "Measurement of new DNA synthesis using EdU incorporation showed 25% increased cell proliferation upon FSTL3 overexpression in gastric cancer cell line SGC-7901." (PMID 34425560, 2021). "The MGC-803 gastric cancer cell line expressing the sh-FSTL3 construct with stable FSTL3 knockdown was compared to the parental cell line (control) for the ability to promote tumor development in the immunocompromised Nude mouse model." (PMID 34425560, 2021). "FSTL3 overexpression promoted a 20% increase in monolayer wound closure compared to control in gastric cancer cell line SGC-7901." (PMID 34425560, 2021). "Our work clearly supports a role for FSTL3 in promoting gastric cancer cell proliferation and migration; furthermore, FSTL3 expression contributes to gastric tumor growth, invasion and metastasis." (PMID 34425560, 2021). "We investigated the close association between follistatin-like 3 (FSTL3) and different cancers, and focused on its role in gastric cancer cell function." (PMID 34425560, 2021). "Further analysis of FSTL3 levels in normal and tumor gastric tissues was analyzed to evaluate the potential role of FSTL3 as a gastric cancer biomarker." (PMID 34425560, 2021). "Our team previously found that FSTL3 is highly expressed in gastric cancer, promoting epithelial-mesenchymal transition (EMT) through the BMP/SMAD signaling pathway." (PMID 34901156, 2021). "In a functional analysis of a family member, termed FSTL3, we provide evidence that a mechanism which directly modulates FSTL3 mRNA levels directly impacts on gastric cancer cell responses which contribute to cancer development and progression." (PMID 34425560, 2021). "Considering the role of FSTL3 in gastric cancer, we hypothesized that FSTL3 may have a similar molecular mechanism in CRC, which was explored in this study." (PMID 34901156, 2021). "Finally, miR-486-5p and FSTL3 levels correlate negatively in an analysis of gene expression in gastric cancer tissues." (PMID 34425560, 2021). "The median FSTL3 expression in gastric cancer tissues was defined as the cut-off value." (PMID 34425560, 2021). "Furthermore, high FSTL3-expressing gastric cancer patients have reduced survival over a 10 yr period." (PMID 34425560, 2021). "However, FSTL3 knockdown promoted a 30% decrease in monolayer wound closure compared to control in gastric cancer cell line MGC-803." (PMID 34425560, 2021). "In order to explore whether FSTL3 regulates gastric cancer cell function, we overexpressed FSTL3 in SGC-7901 cells." (PMID 34425560, 2021). "However, FSTL3 knockdown promoted a 60% decrease in cell migration compared to control in gastric cancer cell line MGC-803." (PMID 34425560, 2021). "FSTL3 expression was increased in gastric cancer compared to control tissues." (PMID 34425560, 2021). "To understand the link between FSTL3 mRNA and miR-486-5p, we evaluated whether such potential regulation impacts on gastric cancer cell responses." (PMID 34425560, 2021). "FSTL3 expression was increased with older age and later stages of gastric cancer disease." (PMID 34425560, 2021). "Overexpression of FSTL3 promoted gastric cancer cell viability, proliferation and migration." (PMID 34425560, 2021). "However, how FSTL3 regulates cancer development and progression is unclear; furthermore, very little is known about FSTL3 regulation of gastric cancer." (PMID 34425560, 2021). "FSTL3 and ADAM12 have similar functions to regulate tumor metastasis and immune infiltration in gastric cancer." (PMID 36325361, 2022). "To further analyze gastric cancer (stomach adenocarcinoma, STAD) increased FSTL3 expression we used the GEO clinical dataset GSE33335." (PMID 34425560, 2021).
gastric cancer (continued). "The previous studies of our group have demonstrated a coactivating relationship between FSTL3 and the BMP/SMAD signaling, showing that it can regulate the SMAD phosphorylation and promote EMT in gastric cancer cells." (PMID 34901156, 2021). "FSTL3 may be a potential binding partner of ADAM12, which is involved in immune infiltration and tumor metastasis in gastric cancer." (PMID 36325361, 2022).
gestational diabetes mellitus (5 papers, 2011 to 2022). "Compared to normal pregnancies, women with gestational diabetes mellitus have decreased maternal and placental FSTL3 concentrations, whereas maternal myostatin concentrations remain unchanged." (PMID 36325361, 2022). "Circulating FSTL-3 was also found to be higher in the first trimester of gestational diabetes." (PMID 26580600, 2015). "This may implicate FSTL3 in the pathogenesis of gestational diabetes." (PMID 36325361, 2022).
asthma (4 papers, 2018 to 2024). "In some patients with asthma, a deficiency in the epithelial expression of FSTL3 leads to an increase in the proportion of activin-A and, consequently, to the activation of airway fibroblasts and further progression of fibrosis." (PMID 34440203, 2021). "FSTL3 shows a reduced expression in the bronchial epithelium of individuals with asthma, which impairs the regulation of fibroblasts involved in remodeling." (PMID 38540988, 2024). "A better understanding of the role of activin-A/FSTL3 signaling in lung fibrosis may lay the foundations for new therapeutic approaches to the treatment and prevention of airway remodeling in asthma and other bronchopulmonary diseases." (PMID 34440203, 2021).
cardiac hypertrophy (4 papers, 2017 to 2023). "After pressure overload induced by transverse aortic constriction, FSTL3 knockout mice exhibited diminished cardiac hypertrophy, reduced left ventricular wall thickness, and left ventricular dilatation." (PMID 36325361, 2022). "FSTL3 is highly expressed in cardiomyocytes and endothelial cells and modulates stress-induced cardiac hypertrophy." (PMID 36325361, 2022). "An increased concentration of FSTL3 or their mRNA are often observed in myocardial hypertrophy, preventing the antihypertrophic effects of activin-A, as FSTL3 is its inhibitor." (PMID 34440203, 2021). "Cardiac specific ablation of FSTL3 reduces cardiac hypertrophy and fibrosis in response to transverse aortic constriction." (PMID 28824923, 2017). "FSTL3 has also been characterized as a stress-induced regulator of cardiac hypertrophy through Smad signalling pathway modulation in a mouse model, opening an opportunity for investigation of the follistatin family of proteins as a therapeutic target for the protection against HF." (PMID 37123479, 2023). "FSTL3 can regulate myocardial fibrotic change and affect myocardial hypertrophy." (PMID 36325361, 2022). "FSTL3 may contribute to myocyte hypertrophy in response to stress stimuli, and the increased levels of FSTL3 in SCM may promote cardiac hypertrophy and fibrosis." (PMID 28824923, 2017). "Inhibiting FSTL3 by neutralizing antibodies may be a potential therapeutic strategy for minimizing its deleterious effects on cardiomyocytes and fibroblasts, thereby inhibiting the development of cardiac hypertrophy and myocardial fibrosis." (PMID 36325361, 2022).
Hypertension (4 papers, 2023 to 2024). The presence of chronic increased pressure in the systemic arterial system. "After adjusting for sex, artery hypertension, smoking, waist circumference and eGFR, serum FSTL3 level explained 24.30% of the association." (PMID 37904173, 2023).
non-small cell lung carcinoma (4 papers, 2020 to 2022). A group of at least three distinct histological types of lung cancer, including non-small cell squamous cell carcinoma, adenocarcinoma, and large cell carcinoma. "A study found that FSTL3 overexpression enhances proliferation and migration of non-small cell lung cancer cells." (PMID 34858481, 2021). "In non-small cell lung cancer (NSCLC), FSTL3 has been found to be closely associated with angiogenic factors based on bioinformatics studies and may serve as a potential anti-angiogenic therapeutic target." (PMID 36325361, 2022). "For instance, FSTL3 overexpression accelerates progression of non-small cell lung cancer cells." (PMID 34858481, 2021). "FSTL3 was upregulated by the lncRNA DSCAM-AS1/miR-122-5p axis and could promote proliferation and migration of non-small cell lung cancer cells." (PMID 33228590, 2020).
atherosclerosis (3 papers, 2022 to 2024). A disease characterized by the build-up of fatty material and calcium deposition in the arterial wall resulting in partial or complete occlusion of the arterial lumen. "Therefore, FSTL3 is linked to atherosclerosis by its role in upregulating CD36 and promoting lipid accumulation in macrophages." (PMID 36325361, 2022). "In summary, FSTL3 signaling contributes to the pathogenesis of atherosclerosis after LDL oxidation by regulating lipid accumulation and inflammation." (PMID 36325361, 2022). "Tumor necrosis factor alpha (TNF-α), which is upregulated during atherosclerosis, promotes FSTL3 transcription by binding to four TNF-α sensitive repeats in its promoter region." (PMID 36325361, 2022). "Histological analysis of patients with atherosclerosis revealed elevated FSTL3 expression." (PMID 36325361, 2022). "In addition to its role in human physiology processes, FSTL3 is also a crucial regulatory factor in the cardiac hypertrophy and myocardial fibrosis, atherosclerosis, via regulating the expression of other proteins including activin A, myostain, Bcl-2." (PMID 36325361, 2022). "Another study proved that up-regulation of FSTL3 in the serum of patients with coronary atherosclerosis could induce lipid accumulation and an inflammatory response in macrophages, thus promoting the occurrence and progression of atherosclerosis." (PMID 37904173, 2023). "Elevated serum FSTL3 was verified in AMI patients with co-existent T2DM and NAFLD, and consistent with the results of previous studies in atherosclerosis patients and AMI animal models." (PMID 37904173, 2023).
Insulin resistance (3 papers, 2011 to 2022). Increased resistance towards insulin, that is, diminished effectiveness of insulin in reducing blood glucose levels. "The FSTL3 gene was initially discovered in patients with in B-cell chronic lymphocytic leukemia, and subsequent studies have shown that the FSTL3 protein is associated with reproductive development, insulin resistance, and hematopoiesis." (PMID 36325361, 2022). "In future it has to be validated if the other most differentially regulated genes between both tissues such as: SGCD, LCE3D, EREG, NDP and CXCL9, FSTL3, PDZK1IP1 could be used as biomarkers related to insulin resistance of adipose or liver tissues respectively." (PMID 21978410, 2011).
intrauterine growth restriction (3 papers, 2008 to 2018). "Elevated FSTL3 transcripts in humans have been linked to hypoxia and intrauterine growth restriction, and in mice overexpression of FSTL3 results in gonadal defects." (PMID 18461179, 2008).
invasive breast carcinoma (3 papers, 2017 to 2023). A carcinoma that infiltrates the breast parenchyma. "FSTL3 expression is inversely associated with tumor size and nuclear grade in invasive breast cancer." (PMID 37953789, 2023). "FSTL3 expression in invasive breast cancer is inversely associated with tumor size and nuclear tumor grade but it does not predict disease relapse in the short term." (PMID 28178680, 2017). "FSTL3 expression in invasive breast cancer is inversely associated with tumor size and nuclear grade but it does not predict disease relapse in the short term." (PMID 28178680, 2017). "FSTL3 is elevated and hastens tumor cell proliferation by antagonizing endogenous activin in invasive breast cancer." (PMID 34858481, 2021). "FSTL3 is facilitated in invasive breast cancer and can boost tumor cell proliferation by antagonizing endogenous activators." (PMID 34858481, 2021). "Here, we expand our previous findings by depicting FSTL3 expression in relation to clinical and pathological features of invasive breast cancer." (PMID 28178680, 2017).